CARD9 (caspase recruitment domain family member 9)
Diseases named in the same sentence as CARD9 in open-access papers (continued):
Sharing a sentence is not in itself a finding about the gene and the disease.
infection (continued). "The neutrophil infiltration to the site of infection is the major innate host defense carried out by the dectin-1 and CARD9 signaling, post-aspergillosis." (PMID 35887412, 2022). "MyD88 activation and CARD9-mediated IFN-γ production are critically involved in preventing the infection of coccidioides in mice." (PMID 35432375, 2022). "Recognition of pathogens by various PRRs initiates the signaling that is propagated via CARD9-mediated signaling to trigger a protective immunity against infection." (PMID 35432375, 2022). "CARD9 transmits the signaling from innate immune cells to T cells, which further enhance the recruitment of neutrophils and macrophages to the areas with infections or damages." (PMID 35432375, 2022). "In later stages of infection, the hematopoietic CARD9 signal amplifies the chemotactic signal and maintains lung neutrophil recruitment." (PMID 35887412, 2022). "Next, we examined the fungal specificity of the Dectin-1 and CARD9 dependence for defense during subcutaneous infection." (PMID 36377664, 2022). "At present, CARD9 has shown an emerging role in the infection immunity of fungi, bacteria, viruses, and parasites; it is partly based on the results of CARD9 KO mice experiments." (PMID 36439825, 2022). "No significant changes in CD107b+ microglia/macrophage numbers were observed between CARD9−/− and WT mice at any time point post infection." (PMID 34209576, 2021). "Conclusively, data show that CARD9 deficiency enhances hippocampal damage with increased neuronal loss, axonopathy and disturbed neurogenesis following acute TMEV infection." (PMID 34209576, 2021). "CARD9−/− mice showed a limited but significant increase in neuronal loss, axonopathy and disturbed neurogenesis in the hippocampus following TMEV infection." (PMID 34209576, 2021). "Even an increased expression of IFN-γ and IL-1β was observed in CARD9−/− mice during the early infection phase (3 dpi), indicating the presence of a CARD9-independent activation of cytokine responses." (PMID 34209576, 2021). "Yamamoto and colleagues determined that defects in CARD9 results in impaired control of Cryptococcus deneoformans strain B3501 infection in mice possibly due to defective Th1- and Th17-type cytokine production." (PMID 31911495, 2020). "Previous studies suggested that the susceptibility of CARD9-deficient mice to C. neoformans is due to a reduced accumulation of IFN-γ-expressing NK cells and memory phenotype T cells during the early stage of infection." (PMID 31911495, 2020). "In mouse models of coccidioidomycosis, recognition of the fungus by Dectin-1 is required to control infection, as is downstream signaling by CARD9." (PMID 32185141, 2020). "Here we report the novel finding that within minutes of infection, T. gondii activates a spleen tyrosine kinase (Syk), PKCδ, CARD9/MALT-1, and NF-κB signaling pathway that is critical for the production of IL-1β in primary human monocytes." (PMID 31449558, 2019). "CARD9 is a central signaling molecule in the innate immune system, which is essential for host defense against infection." (PMID 30906296, 2019). "Infection of either the PKCδ KO or CARD9 KO THP-1 cells with T. gondii resulted in reduced IL-1β release compared to infection of the EV cells." (PMID 31449558, 2019). "CARD9 is primarily expressed in immune cells including neutrophils and is required for responses to external infection." (PMID 29940016, 2018). "Our data show increased IL-1β protein expression in Card9−/− BMDMs at 2 and 6 h post infection compared with WT cells." (PMID 27670879, 2016). "WT and Card9−/− mice infected with S. Typhimurium (strain M525P) had similar bacterial burdens in the spleen at days 1, 3 and 7 post infection." (PMID 27670879, 2016). "Card9−/− macrophages secreted 2.5 times more IL-1β than WT BMDMs at both 6 and 24 h post infection, time points known to involve NLRP3 activity in response to Salmonella infection." (PMID 27670879, 2016).
infection (continued). "If CARD9 is a central regulator of the inflammatory response to pathogens then signalling through other CARD9-dependent PRRs that recognize salmonellae should also be altered in response to infection." (PMID 27670879, 2016). "In mouse models of fungal challenge, Card9 genetic deletion abolishes the ability to control systemic Candida albicans infections, with 100% mortality observed as early as 72 h post-infection." (PMID 27092298, 2016). "Consistent with this idea, overstimulation of NOD2 at the same time as infection with S. Typhimurium leads to a CARD9- and NOD2-dependent decrease in pro-IL-1β expression." (PMID 27670879, 2016). "Card9−∕− animals were also found to be mildly susceptible to mucosal candidiasis; however, this was only evident during secondary infection suggesting that the dependence on Card9 lies within the adaptive immune compartment for this particular disease." (PMID 27092298, 2016). "We observed that PR8-infected WT mice appeared visibly ill with ruffled fur and reduced oral intake during the 6 to 10 days after infection, whereas Card9–/–mice appeared more active than WT mice." (PMID 26627732, 2015). "At 24 hours post-infection, WT and Card9-/- brains had similar levels of these chemokines despite a 10-fold higher fungal load in Card9-/- brain tissue." (PMID 26679537, 2015). "We found that Card9-/- mice had similar bacterial burdens and accumulation of neutrophils in the brain compared to WT mice at 48 hours post-infection." (PMID 26679537, 2015). "At 72 hours post-infection, Card9-/- mice exhibited dramatically greater brain fungal burdens (over 1000-fold) compared to WT animals." (PMID 26679537, 2015). "Consistent with their activity, the final survival rate up to day 21 after infection was dramatically improved in Card9–/–mice (~80%) as compared with WT mice (~40%)." (PMID 26627732, 2015). "We found that, in line with previously reported findings, Card9-/- mice had significantly increased kidney fungal burdens at both 24 and 72 hours post-infection." (PMID 26679537, 2015). "Host defense against A. fumigatus involves the activation of two host signal transducers, MyD88 and CARD9, leading to neutrophil recruitment to the infection site." (PMID 25621893, 2015). "Card9-/- brains had similar neutrophil numbers with WT brains at 72 hours post-infection; strikingly, these numbers were similar to those observed in the uninfected brain." (PMID 26679537, 2015). "MyD88(−/−)CARD9(−/−) mice rapidly and universally succumbed to this infectious inoculum, while the mice in all other groups survived the infection." (PMID 25621893, 2015). "We found that both Cxcl1 and Cxcl2 were significantly induced following infection in both WT and Card9-/- mice whereas Cxcl5 was poorly induced." (PMID 26679537, 2015). "Using this approach, we found no defect in the ability of Card9-/- neutrophils to traffic into the infected brain, since the relative ratio of WT:Card9-/- neutrophils remained unchanged before and after infection." (PMID 26679537, 2015). "To investigate if this was also true in Card9-/- mice, we calculated the relative frequency of multiple lymphoid and myeloid cell populations in the brain following infection by FACS." (PMID 26679537, 2015). "The first steps taken to address the importance of the Mincle-Syk-Card9 pathway in the dealing of innate immune cells with infecting mycobacteria were in vitro infection experiments of macrophages with M. bovis BCG or MTB." (PMID 23355839, 2013). "Microglia indeed showed increased CD45 at day 4 p.i. in both CARD9-deficient strains but not WT mice, consistent with their activation during infection at this time point." (PMID 40424070, 2025). "Thus, Y91HKI mice phenocopied Card9–/– mice during high-dose infection with respect to acuity, morbidity, and mortality, demonstrating that this protein residue was essential for CARD9 function in mice." (PMID 40424070, 2025).
infection (continued). "CARD9-deficient mice did not clear the infection in the liposomal control treatment and showed fungal burden in both the brain and kidney." (PMID 40424070, 2025). "Weight loss is statistically significant but small in CARD9-deficient mice within the first week of infection; thus, severe morbidity is absent during this time compared with the high-dose model." (PMID 40424070, 2025). "Experimental studies have implicated Card9 in host resistance against C. neoformans; however, the mechanisms that are associated with susceptibility to progressive infection are not well defined." (PMID 38921420, 2024). "Finally, following intratracheal infection with C. neoformans 52D, Card9 mutant mice have a greater incidence of fungal dissemination and significantly higher fungal burden in the brain that results in 100% mortality." (PMID 38921420, 2024). "CARD9-deficient cells revealed no impairment in phagocytosis and killing ability during A. fumigatus and certain Candida species infections." (PMID 38473845, 2024). "Since the signals emanating from the interaction of multiple CLR with MTB are transmitted through SYK-CARD9, it is not surprising that CARD9-deficient mice are highly susceptible to infection with MTB and succumb with high bacterial burden in the organs." (PMID 36753434, 2023). "Indeed, CARD9 KO mice fail to develop adaptive Th17 cells or produce IL-17A in response to infection with Candida or Phialophora verrucosa." (PMID 35432375, 2022). "CARD9 signaling is involved in innate immunity and the development of adaptive immune system, and has been recognized as an important protective mechanism against infections of selected fungi, bacteria, and viruses." (PMID 35432375, 2022). "Notably, the specific function of Card9 is different in different cell types, thus controlling the cellular specificity in the host’s response to infection." (PMID 35618701, 2022). "Card9 mediates signals from pattern recognition receptors to downstream signaling pathways and activates proinflammatory cytokines and anti-inflammatory cytokines via an innate immune response to clear an infection." (PMID 32256671, 2020). "We show that CARD9-deficient mice inoculated with LW10 demonstrate significant increases in pulmonary fungal burden and dissemination to splenic tissues and succumbed to infection with LW10, whereas WT mice were able to resolve the infection." (PMID 31911495, 2020). "However, CARD9-mediated innate responses in pulmonary DCs were dispensable for protection against IAV in a murine infection model." (PMID 30917612, 2019). "Emerging studies indicated that CARD9 was also associated with sterile inflammation disease in the absence of pathogen infections." (PMID 29352133, 2018). "Unexpectedly, CARD9 deficiency had no influences on AM accumulation in the lungs at day 1 after infection with C.n-D strain WM629." (PMID 30131805, 2018). "However, in that model, Card9 was only partially required in the later stages of infection for neutrophil accumulation in the infected lung." (PMID 27092298, 2016). "This suggests that CARD9 may function as a signalling hub coordinating the cellular response to infection and permitting a rapid integrated inflammatory response to a range of PRRs." (PMID 27670879, 2016). "We propose that CARD9 is a central signalling hub that can negatively or positively regulate proinflammatory signalling to coordinate a pathogen-specific host inflammatory response to infection." (PMID 27670879, 2016). "Indeed, we found a profound decrease in neutrophil accumulation in the Card9-/- brain at 24 hours post-infection compared with WT animals." (PMID 26679537, 2015). "We first assessed whether Card9 is critical for the production of neutrophil progenitors in the bone marrow and egress of these cells into the peripheral blood after infection." (PMID 26679537, 2015).
infection (continued). "In a second scenario, MyD88- and CARD9-coupled signals may act in distinct cellular compartments in the lung within the same time phase post-infection (p.i.)to induce chemokines and coordinate innate immune responses." (PMID 25621893, 2015). "Since β-integrin 2 induction was greater in Card9-/- brains at 72 hours post-infection, we assessed whether its induction in the Candida-infected brain is fungal load-dependent by infecting WT mice with high and low brain fungal burdens." (PMID 26679537, 2015). "At 72 hours post-infection, chemokine levels decreased in WT mice in parallel with falling tissue fungal burden, whereas chemokine levels in Card9-/- brains remained stable relative to 24 hours post-infection despite a further dramatic increase in brain fungal burden." (PMID 26679537, 2015). "Additionally, CARD9 was found to be required for the production of inflammatory cytokines after infection with RNA viruses, such as vesicular stomatitis virus and encephalomyocarditis virus, by regulating NF-κB signaling through RIG-I and Mda521." (PMID 26627732, 2015). "Our model identifies that loss of CARD9 function associates with impaired tissue control of low fungal burden and cerebral multinucleated giant cells/granulomata, coupled with abnormal influx of Ly6C+ moDC and defective BMDM responses, ultimately contributing to indolent infection with late disease." (PMID 40424070, 2025). "Thus, CARD9 could be a potential target for prevention and treatment of a variety of diseases including infections, CVDs, and cancer." (PMID 35432375, 2022). "There have been no previous case reports of TM infection in individuals with CARD9 gene mutations." (PMID 34234782, 2021). "However, CARD9 deficiency enabled titan cell formation by the LW10 strain, where titan cells became the dominant population in the infected lungs, similarly to the H99 strain infections." (PMID 31911495, 2020). "Moreover, CARD9 deficiency completely blocked AM accumulation and significantly reduced secretion of pro-inflammatory cytokine including TNF-α and IL-6 in the lungs on day 1 after infection with C.g-B." (PMID 30131805, 2018). "Indeed, histopathology revealed that neutrophils could be seen to crowd around hyphae in WT brains at 24 hours post-infection, whereas very few of these cells were observed in Card9-/- brains." (PMID 26679537, 2015). "Furthermore, we show that CARD9-deficient mice and humans are unable to produce the molecules (chemoattractants) needed to recruit neutrophils to the site of infection, thus identifying the mechanism for the striking absence of these cells in the infected CNS." (PMID 26679537, 2015). "Local infection provides the necessary CXC signal to induce neutrophil recruitment indirectly, in which CARD9 has been proven to play a crucial part." (PMID 36439825, 2022). "This may be the consequence of the CARD9-dependent, but Syk-independent, chemokine production observed in C. parapsilosis-treated macrophages that could allow for more efficacious leukocyte recruitment to the site of infection in Syk−/− chimeras than in CARD9−/− chimeras." (PMID 34465030, 2021). "Notably, we found that CARD9 deficiency did not increase virus titers and the amount of viral RNA in the lungs, but instead significantly accelerated viral clearance in the later stage (day 8) of infection." (PMID 26627732, 2015). "We have prev iously shown that a small molecule, termed BRD5529, an inhibitor of CARD9, can reduce macrophage inflammatory signaling responses to Pneumocystis b-glucans, but this agent has never been tested in a whole animal infection model." (PMID 39745390, 2025). "The absence of CARD9 results in various infection outcomes depending on the pathogen and the organ or compartment of infection." (PMID 39745390, 2025). "The consequence of these broad Card9-dependent defects is universal mortality from an otherwise non-lethal infection model." (PMID 38921420, 2024).
infection (continued). "A comparable lung fungal burden of 107 CFU was observed at day 7 post-infection in both strains, suggesting that the Card9-dependent signaling did not have a marked effect on the initial host response to C. neoformans." (PMID 38921420, 2024). "Third, we did not determine which CLRs activate Card9 in response to intratracheal infection with C. neoformans 52D." (PMID 38921420, 2024). "These striking differences in fungal burdens were recently found to be due to candidalysin-dependent induction of IL-1β and CXCL1 secretion from CARD9+ microglial cells, which function to recruit CXCR2-expressing neutrophils to the brain to control the infection and hence reduce fungal burdens." (PMID 31401652, 2019). "Both of these studies used C. albicans to initiate infection and did not investigate the dependence on Card9 for these activities." (PMID 27092298, 2016). "At 2 and 6 h post infection, both WT and Card9−/− BMDMs showed similar levels of cellular viability in the presence or absence of glibenclamide, while MCC950 slightly inhibited cell death in Card9−/− BMDM." (PMID 27670879, 2016). "While we observed a delayed induction in the expression of α-integrin X and α-integrin L in infected Card9-/- brains, these differences were not evident at 72 hours post-infection." (PMID 26679537, 2015). "According to previous reports, during infection with several RNA viruses, NOD2 is activated and leads to the activation of a protective innate immune response mediated by interactions with adaptors including RIP2, MAVS, OAS2, CARD9, etc., resulting in activities against the pathogens." (PMID 38668261, 2024). "Although CARD9 deficiency did not alter the leukocyte recruitment profile following infection with strain LW10, we performed a histological examination of lung tissue sections prepared from WT and CARD9-deficient mice inoculated with either C. neoformans strain H99 or LW10." (PMID 31911495, 2020). "We re-infected WT and Card9–/–mice on day 21 after their first infection (representing the second infection) and analyzed the production of virus-specific antibodies as well as the development of virus-specific CD8+ T cells on day 14 after the second infection." (PMID 26627732, 2015). "However, CARD9−/− mice were not protected from infection, suggesting that CM develops independently of CARD9 despite its upregulation during disease." (PMID 24330199, 2014). "They found that CARD9−/− mice could not control infection (even when challenged with a BAD1 deletion hypovirulent mutant), and the mutant mice did not respond to immunization with killed B. dermatitidis yeast, indicating that a CLR was required for both innate and acquired immunity." (PMID 32545735, 2020). "Notably, while WT mice recruited high numbers of neutrophils to the brain early after infection, there was no significant increase in neutrophil numbers or frequency between uninfected and infected Card9-/- brains at any time point after infection, despite dramatic tissue fungal proliferation." (PMID 26679537, 2015). "Mononuclear cell aggregation at fungal lesions in the brain correlated with increased MHCII+Ly6C+ monocyte numbers at day 1 after infection in WT and Y91HKI mice, but not in Card9-/– mice." (PMID 40424070, 2025). "However, it is possible that the absence of Syk and CARD9 is sufficient for a failure in the development of adaptive immunity, and innate mechanisms alone are unable to prevent the proliferation of host-adapted C. parapsilosis cells over an extended period of infection." (PMID 34465030, 2021). "However, the potential function and molecular mechanism of Card9‐Bcl10 complex in SAP still need further investigation using a rat model, supporting that PMBCs in the absence of infection shared a similar complex in the production of inflammatory cytokines or not." (PMID 26893103, 2016).